TMEM87B (transmembrane protein 87B)
Description:
May be involved in retrograde transport from endosomes to the trans-Golgi network (TGN).
Synonyms: FLJ14681
Tractability: Antibody: UniProt predicts a signal peptide or a membrane-spanning region. PROTAC: ubiquitination databases record sites on it; its protein half-life has been measured.
Gene: Protein-coding gene on chromosome 2 (112,055,269 to 112,119,318, forward strand). Ensembl gene ENSG00000153214.
Subcellular location: Golgi apparatus membrane
Subcellular location (Human Protein Atlas): Golgi apparatus; Vesicles
Gene Ontology:
Biological process: retrograde transport, endosome to Golgi
Cellular component: Golgi cisterna membrane; cytosol; Golgi membrane; membrane
Genetic constraint (gnomAD): Loss-of-function variants: 56 observed, 52.58 expected, observed/expected ratio (o/e) 1.07, 90% interval 0.86 to 1.33. The upper end of that interval is the gene's LOEUF score, 1.33, which puts it in group 5 of 6, group 1 being the genes least tolerant of losing a copy. Missense variants: 475 observed, 501.39 expected, observed/expected ratio (o/e) 0.95, 90% interval 0.88 to 1.02. Synonymous variants: 182 observed, 172.96 expected, observed/expected ratio (o/e) 1.05, 90% interval 0.93 to 1.19.
Homologues: Orthologues: chimpanzee TMEM87B (99% identical), dog TMEM87B (89% identical), rat Tmem87b (89% identical), mouse Tmem87b (88% identical), rabbit TMEM87B (86% identical), pig TMEM87B (85% identical), guinea pig TMEM87B (80% identical), tropical clawed frog tmem87b (59% identical), Drosophila melanogaster CG17660 (39% identical), Caenorhabditis elegans C52B9.4 (33% identical), zebrafish TMEM87B (27% identical), Drosophila melanogaster CG12121 (15% identical), and 1 more. Paralogues in human: TMEM87A (46% identical), GPR107 (17% identical), GPR108 (15% identical).
Diseases named in the same sentence as TMEM87B in open-access papers:
TMEM87B is named in the same sentence as 7 diseases in open-access papers, as found by Europe PMC text mining. Sharing a sentence is not in itself a finding about the gene and the disease. The quoted sentences say what the papers report.
cardiac hypertrophy (1 paper, 2020). "Cardiac hypoplasia is caused by the deletion of tmem87b in zebrafish while mice overexpressing Nab1 are resistant to cardiac hypertrophy." (PMID 33031577, 2020).
congenital heart defects (1 paper, 2023). "FBLN7 and TMEM87B in 2q13 locus could confer susceptibility to congenital heart defects." (PMID 36816019, 2023).
developmental delay (1 paper, 2025). "Additionally, FBLN7 and TMEM87B, alone or in combination with other genes in the region, may also be involved in neurological features such as developmental delay - phenotypes that are more difficult to assess in zebrafish models." (PMID 40979016, 2025).
liver cancer (1 paper, 2018). An epithelial or non-epithelial malignant neoplasm that arises from the liver. "Interestingly, recurrent MERTK fusions are singletons in each individual cancer type with TMEM87B, and PRKACA fusions are observed only in liver cancer with DNAJB1." (PMID 29617662, 2018).
restrictive cardiomyopathy (1 paper, 2025). A type of heart disorder referring to the inability of the ventricles to fill with blood because the myocardium (heart muscle) stiffens and looses its flexibility. "Notably, a potentially deleterious TMEM87B variant was identified in a patient with a hemizygous 2q13 microdeletion, suggesting a recessive condition characterized by CHD and restrictive cardiomyopathy." (PMID 41427249, 2025).
TMEM87B also shares sentences with these, for which no sentence is quoted: cancer (2 papers); Cluster headache (1).